RXRA (retinoid X receptor alpha)
Diseases named in the same sentence as RXRA in open-access papers (continued):
Sharing a sentence is not in itself a finding about the gene and the disease.
hematological malignancies (1 paper, 2021). "These genes were regulated by RXRα and GATA1, which are involved in hematological malignancies." (PMID 34832908, 2021).
myopathy (1 paper, 2014). A disease of the muscle in which the muscle fibers do not function properly. "The dysregulation of nuclear receptors, such as VDR and RXRα in muscle cells, has also been postulated to result in myopathy via their effects on muscle structural integrity and metabolism." (PMID 24782788, 2014).
neurodegenerative disease (1 paper, 2019). A disorder of the central nervous system characterized by gradual and progressive loss of neural tissue and neurologic function. "The nuclear receptors (NRs) RARα, RXRα, PPARα, and PPARγ represent promising pharmacological targets for the treatment of neurodegenerative diseases." (PMID 30759808, 2019). "Recently, it has also been shown that the stimulation of RARα, RXRα, and PPARα/γ may be beneficial in treating neurodegenerative diseases." (PMID 30759808, 2019). "Altogether, the ability of RAR and PPAR stimulation to affect Aβ accumulation suggests that compounds with broad agonist activity toward RARα, RXRα, and PPAR-α and -γ could represent useful pharmacological tools to provide novel inroads for the treatment of neurodegenerative diseases." (PMID 30759808, 2019).
RXRA also shares sentences with these, for which no sentence is quoted: head and neck squamous cell carcinoma (3 papers); kidney diseases (3); glucose metabolism disorder (2); Kaposi's sarcoma (2); lipodystrophy (2); liposarcoma (2); measles (2); myopia (2); osteoporosis (2); periodontitis (2); preeclampsia (2); rubella (2); skin cancer (2); squamous carcinoma (2); stomach cancer (2); acne vulgaris (1); acute myocardial infarction (1); adenocarcinoma (1); adenomyosis (1); allergic rhinitis (1); Allergy (1); amyotrophic lateral sclerosis (1); antithrombin deficiency (1); brain tumors (1); cannabis dependence (1); chronic myeloid leukemia (1); cognitive decline (1); colon adenoma (1); contact dermatitis (1); Corneal Disease (1).
A further 47 diseases each share a sentence with RXRA in 1 paper.